SNORA65 (small nucleolar RNA, H/ACA box 65)
Synonyms: U65; RNU65
Gene: Small nucleolar RNA gene on chromosome 9 (127,448,501 to 127,448,630, reverse strand). Ensembl gene ENSG00000201302.
Gene Ontology:
Biological process: RNA processing
Cellular component: nucleolus
Homologues: Orthologues: macaque SNORA65 (99% identical), chimpanzee SNORA65 (98% identical), pig SNORA65 (96% identical), mouse Snora65 (92% identical), rat Snora65 (92% identical), rabbit SNORA65 (86% identical).
Diseases named in the same sentence as SNORA65 in open-access papers:
SNORA65 is named in the same sentence as 7 diseases in open-access papers, as found by Europe PMC text mining. Sharing a sentence is not in itself a finding about the gene and the disease. The quoted sentences say what the papers report.
lung carcinoma (2 papers, 2017 to 2021). "SNORA65 overexpression in metastasised oral squamous cell carcinoma (OSCC), SNORA21 and SNORA47 in lung cancer were also reported previously." (PMID 27965463, 2017). "Suppression of SNORA65 and SNORA7A/7B inhibited growth and proliferation of lung cancer cells." (PMID 33288886, 2021). "Interestingly, SNORA65 has been correlated with metastasization in OSCC, SNORA21 and SNORA47 with lung cancer." (PMID 27965463, 2017). "Thus, our results indicate that depletion of SNORA65 and SNORA7A/7B inhibits proliferation and tumorigenicity of lung cancer cells which does not associate with immediate apoptosis or cell cycle arrest." (PMID 33288886, 2021).
ameloblastoma (1 paper, 2017). The most common odontogenic tumor, arising from the epithelial component of the embryonic tooth and usually affecting the molar-ramus region of the mandible or maxilla. "We have in this study reported significantly higher expression of a number of snoRNAs (SNORD116-25, SNORA11, SNORA21, SNORA47 and SNORA65) in ameloblastoma." (PMID 27965463, 2017). "Further validation in an independent cohort points out the long non-coding (lncRNAs) and small nucleolar RNA (snoRNAs): LINC340, SNORD116-25, SNORA11, SNORA21, SNORA47 and SNORA65 as a distinct ncRNA signature of ameloblastoma." (PMID 27965463, 2017). "The result corroborates that SNORA65, SNORA21, SNORA47, SNORD116-25 and LINC340, which were validated here by RT and qPCR assays, belonged to the top most significantly expressed snoRNAs and lncRNAs in ameloblastoma." (PMID 27965463, 2017).
multiple myeloma (1 paper, 2017). "Furthermore, down-regulation of SNORA65 has been reported in chemo-sensitive ovarian adenocarcinoma compared to chemo-resistant tumours, and deregulation of SNORD116-25 in multiple myeloma." (PMID 27965463, 2017).
tumour (2 papers, 2017 to 2025). "Top hits include changes in transcriptional regulation (ZNF385B, SNORA65), tumour microenvironment (COL1A2, COL3A1), and metastatic processes (UCHL1, SUCNR1, THY1)." (PMID 40890143, 2025). "It was found that the accumulated ncRNA levels (LINC340, LINC342, SNORD116-25, SNORA11, SNORA21, SNORA47, SNORA65; r = 0.5789, p-value = 0.0075) had a positive but moderate correlation with tumour size." (PMID 27965463, 2017).
Malignant tumors (1 paper, 2026).
SNORA65 also shares sentences with these, for which no sentence is quoted: oral squamous cell carcinoma (1 paper); ovarian adenocarcinoma (1).